MMP9 (matrix metallopeptidase 9)
Diseases named in the same sentence as MMP9 in open-access papers (continued):
Sharing a sentence is not in itself a finding about the gene and the disease.
ovarian carcinoma (continued). "MMP-9 and MMP-2 have been found consistently upregulated in ovarian cancer and are associated with poor prognosis." (PMID 23340649, 2013). "The current study extended this finding to examine the protein expression of MMP-9 in tissue and serum of primary and recurrent/chemoresistant ovarian cancers." (PMID 23340649, 2013). "Tissue inhibitor of matrix metalloproteinases (TIMP) are naturally occurring inhibitors of MMPs, except for TIMP1 and TIMP2, which help activate MMP-2 and MMP-9, thereby playing a role in migration and invasion in ovarian cancer." (PMID 23591839, 2013). "To investigate the role of MMP-9 in recurrent/chemoresistant ovarian cancer we carried out functional inhibition of the gene using a chemical inhibitor (2R)-2-[(4-Biphenylsulfonyl) amino]-3 phenylpropionic acid (C21H19NO4S) (MMP-9/MMP-2i)." (PMID 23340649, 2013). "After matrix metalloproteinase 9 (MMP −9) activity was inhibited by MMP-9 Inhibitor I, the interaction between mouse embryos and human ovarian cancer cells HO8910PM was observed." (PMID 22672566, 2012). "For example, studies demonstrated that fibronectin increases the secretion of matrix metalloproteinase-9 (MMP-9) in ovarian cancer and stimulate the growth of non-small cell lung carcinoma via PI3K/Akt signaling pathway." (PMID 22321604, 2012). "At present in rectal cancer, bladder cancer, cervical cancer, ovarian cancer and other tumors, MMP-9 was found to be involved in the invasion and metastasis of cancer cells and tumor angiogenesis." (PMID 22672566, 2012). "The mouse embryo was still able to invade human ovarian cancer cells after MMP-9 activity was inhibited." (PMID 22672566, 2012). "In another study assessing MMP-2, MMP-9 and MT1-MMP in 77 patients with ovarian cancer, strong epithelial MT1-MMP and stromal MMP-9 and FIGO stage were independently associated with shorter survival." (PMID 22200690, 2012). "In the experiment group supplemented with MMP-9 Inhibitor I, the embryo can still adhere to human ovarian cancer cells and push away tumor cells to form their own growth space, exhibiting invasive behavior to tumor cells." (PMID 22672566, 2012). "It is well established that increased MMP-2 and MMP-9 expression in ovarian cancer correlates negatively with prognosis and survival." (PMID 22022379, 2011). "A recent study showed that JNK, but neither ERK1/2 nor p38 MAPK, was critical for GnRH-mediated production of MMP-2 and MMP-9 in human ovarian cancer cells." (PMID 20074375, 2010). "We next compared plasma protein levels of VEGF and MMP-9 in pre-treatment and post-treatment ovarian cancer patients with those of healthy controls." (PMID 20334653, 2010). "In this study, we showed that overexpression of Lewis (y) increased MMP-2 and MMP-9 expression to promote migration and invasion of ovarian cancer cells." (PMID 21151448, 2010). "Increased transcriptional activity of the MMP-9 promoter in Ras-transformed ovarian carcinoma cells has also been shown to be mediated by MAP kinases." (PMID 12177807, 2002). "This study investigated the impact of siRNA-mediated MEG3 silencing in the context of dendrosomal nanocurcumin (DNC) and Oxaliplatin (OXA) treatments on ovarian cancer cell lines, focusing on the expression of genes associated with apoptosis and metastasis, including Bcl-2, BAX, MMP-2, and MMP-9." (PMID 41480643, 2026). "Less frequently assessed markers also offered insight: MMP-9 in combination with CRP aided in detecting postoperative complications, whereas the VEGF levels in ascitic fluid were associated with disease progression and stage in ovarian cancer." (PMID 41010973, 2025). "In addition, OA-Ir and OA-Ru effectively suppressed the metastasis of ovarian cancer cells through the mechanism of suppressing MMP2/MMP9 and disrupting F-actin dynamics." (PMID 40362572, 2025). "Elevated MMP-9 levels have also been reported in patients with ovarian cancer and depression." (PMID 40563747, 2025).
ovarian carcinoma (continued). "Also, ovarian cancer dissemination was suppressed in vitro and in vivo via lower MMP-9 expression, leading to better long-term survival in a mouse model." (PMID 38504975, 2024). "Moreover, we identified a novel link between MICALL2 and MMP9 in the regulation of invadopodia formation and the invasion of ovarian cancer cells." (PMID 38203692, 2023). "In addition, the SMM extract significantly inhibited cell invasion and the expression levels of matrix metalloproteinase (MMP)-2 and MMP-9 in ovarian cancer cells." (PMID 37507925, 2023). "Notably, MMPs (such as MMP-2 (gelatinase A) and MMP-9 (gelatinase B)) have been introduced to degrade type IV collagen to facilitate cancer cell invasion and metastasis in ovarian cancer." (PMID 36658640, 2023). "In particular, MMP-2 and MMP-9 play critical roles in the metastasis of human ovarian cancer cells." (PMID 37507925, 2023). "Gelatinase MMPs such as matrix metalloproteinase − 9 (MMP-9) and matrix metalloproteinase − 2 (MMP-2) overexpression are associated with oral cancer, colorectal tumor, bladder carcinoma, retinoblastoma, pancreatic cancer, and ovarian cancer." (PMID 37798646, 2023). "It appears controversial whether MMP9 contributes to better or worse clinical outcomes in ovarian carcinoma." (PMID 37296952, 2023). "Additionally, the positive correlation between HK2 and p-Akt1, fibronectin, MMP9 expression in human ovarian cancer samples was verified by using Pearson correlation analysis." (PMID 35953860, 2022). "Soluble B7-H3 had been confirmed to facilitate metastasis through increasing the formation of premetastatic niches through regulating the expression of VEGF in tumor cells, while VEGF induced the expression of MMP-9 was crucial for the metastasis of ovarian cancer cells." (PMID 35116068, 2022). "In addition, it was indicated that expression of MMP-9 is increased by mediated of EGF (epidermal growth factor) in ovarian cancer cells." (PMID 35538133, 2022). "Additionally, an ovarian cancer mouse model found that TAMs were major sources of MMP-9, and MMP9-producing TAMs, were positively related to tumor angiogenesis and tumor growth." (PMID 36419156, 2022). "Therefore, we investigated the effects of citromycin on MMP2 and MMP9 expression levels in human ovarian cancer cells." (PMID 35621926, 2022). "MMP9 is considered a potential biomarker for tumors, including ovarian cancer." (PMID 35299895, 2022). "Accordingly, we employed the RNA velocity to explore the ovarian cancer lineage trajectories and we found that a small number of CD14_mono evolved toward MMP9_macro, while LYVE1_macro evolved toward CCL18_macro as well as toward MMP9_macro." (PMID 35935940, 2022). "By contrast, some more recent research demonstrated that IL-8 promoted epithelial to mesenchymal transition (EMT) by increasing the MMP-2, MMP-9 and EpCAM expression, and stimulated the anchorage-independent growth, proliferation, angiogenic potential, adhesion and invasion in ovarian cancer cells." (PMID 35867729, 2022). "In this study, further study also demonstrated that HK2 could elevate the expression of EMT-related factors in human ovarian cancer cell, like fibronectin, MMP9, CHD2, Vemintin, ZEB1 and ZEB2." (PMID 35953860, 2022). "MMP2 and MMP9 play important roles in the migration and invasion of ovarian cancer cells." (PMID 35621926, 2022). "PGI2 has been described to act as an anti-metastatic mediator in lung cancer mouse models and to suppress ovarian cancer cell invasion by MMP2/MMP9 downregulation in vitro, whereas other studies reported an association of PTGIS expression with reduced survival of breast and ovarian cancer patients." (PMID 36551640, 2022). "For example, the migration and invasion ability could be increased by overexpressing TP72‐AS1 by positively regulating matrix metalloproteinase (MMP)‐2 and MMP9 in ovarian cancer cells." (PMID 34288373, 2021).
ovarian carcinoma (continued). "Furthermore, we also detected the expression of PCNA and MMP9 in ovarian cancer cell lines after transfection with PC-1 siRNA." (PMID 33635867, 2021). "However, the concurrent enhanced expression of TIMP-2, -3 and MMP-9, -11, -14 observed in ovarian carcinomas is conflicting with the potential inhibitory actions of the TIMPs on MMPs and requires further investigation." (PMID 35047406, 2021). "Therefore, the joint analysis of S100A11 and MMP-9 is very important in the study of drug-resistance mechanisms in ovarian cancer." (PMID 33763485, 2021). "Moreover, Hexokinase 2 regulates the metastasis, invasion, and cell stemness of ovarian cancer cells through the FAK/ERK1/2/MMP9/NANOG/SOX9 signal transduction pathways." (PMID 34596006, 2021). "The present study, therefore, aims to investigate the potential role of the miRNAs miR-138, -210 and -335 and their downstream effector, HIF-1α and MMP9, as well as changes induced by sevoflurane or desflurane, which are commonly used clinically on ovarian cancer cell biology and malignancy." (PMID 33673181, 2021). "Although this observation may suggest an inverse relationship between GSK3β and MMP protein expression, our immunohistochemical data indicate that both GSK3β and MMP-9 are overexpressed in advanced-stage ovarian cancer." (PMID 34023818, 2021). "In addition, we found that ERK activation and MMP-9 expression were required for ovarian cancer cell migration by CCL7." (PMID 34206004, 2021). "We conclude that the GSK3β/ETS1/MMP-9 axis may regulate the biological aggressiveness of ovarian cancer and can serve as a prognostic factor in patients with this malignancy." (PMID 34023818, 2021). "The expressions of VEGF, MMP-2, and MMP-9 were increased in a stressed rodent model of ovarian carcinoma and another stressed rodent model of lung carcinoma, and the same upregulations were detected in nasopharyngeal carcinoma tumor cells treated with norepinephrine." (PMID 34869378, 2021). "It is conceivable that – in addition to the GSK3β/Snail pathway – the GSK3β/ETS1/MMP-9 axis may be involved in ovarian cancer spread." (PMID 34023818, 2021). "Therefore, CQDs/Cu2O selectively mediated of ovarian cancer SKOV3 cells death mainly through decreasing the expression of MMP-2, MMP-9, F-actin, and VEGFR2, meanwhile CQDs/Cu2O caused apoptosis of SKOV3 via S phase cell cycle arrest." (PMID 33663548, 2021). "We also analyzed phospho-ETS1 and MMP-9 in ovarian cancer tissues." (PMID 34023818, 2021). "In addition, recently study revealed that HK2 regulated cell migration, invasion, and stemness via FAK-ERK1/2/-MMP9-NANOG-SOX9 signaling cascades in ovarian cancer cells." (PMID 33324557, 2020). "In ovarian cancer patients, melatonin treatment may control cell invasion and metastasis by decrease in MMP9 activity." (PMID 32499868, 2020). "In addition to promoting invasion by remodeling the ECM, MMP-9 also facilitates angiogenesis and cell adhesion in ovarian cancer." (PMID 33256016, 2020). "In addition, SLPI was shown to stimulate ovarian cancer invasion and this function was partly mediated by its serine protease inhibitory activity attenuating MMP-9 release." (PMID 31462893, 2019). "In ovarian carcinoma cells, MMP-9 regulates the posttranslational modification of E-cadherin." (PMID 30931081, 2019). "High mRNA expression of MMP-2, MMP-9, MT1-MMP and TIMP-2 in primary ovarian tumors and stromal compartments was associated with poor survival in ovarian cancer patients, suggesting that MMP-2, MMP-9, MT1-MMP and TIMP-2 are valid markers of poor survival in advanced-stage ovarian carcinoma." (PMID 29393911, 2018). "MMP-9 has recently been found to be a biomarker of ovarian cancer." (PMID 30262739, 2018). "MMP2 was upregulated 3-fold and MMP-9 6.5-fold in ovarian cancer." (PMID 29581841, 2018). "Next, we assessed MMP-2 and MMP-9 activity in ovarian cancer cell lines." (PMID 29581841, 2018).
ovarian carcinoma (continued). "Additionally, epithelial ovarian cancer cells secrete Gal-7, which through matrix metalloproteinase 9 (MMP-9) promotes invasiveness." (PMID 29320431, 2018). "Moreover, activation of p70S6K1 in human ovarian carcinoma cells in response to stimulation by hepatocyte growth factor (HGF) also led to increased expression of matrix metalloproteinase 9 (MMP9) and higher migration rate of these cells." (PMID 30705751, 2018). "In this study, we tested our hypothesis that STAT3 regulates MMP-9 gene expression in epithelial ovarian cancer." (PMID 28859117, 2017). "In addition, in the past two years, an increasing number of studies have revealed the relationship between MMP-9 and oesophageal squamous cell carcinoma, ovarian cancer, nasopharyngeal carcinoma, Ewing sarcoma, and bladder cancer." (PMID 29228747, 2017). "The systematic review on 12 polymorphisms suggested that MMP2 C-735T, MMP7 A-181G, MMP8 rs11225395, MMP9 rs6094237, MMP12 rs2276109, MMP20 rs2292730, MMP20 rs12278250, MMP20 rs9787933 might have a potential effect on ovarian cancer risk." (PMID 28957437, 2017). "We assessed the expression levels of MMP-2 and MMP-9 in mifepristone-treated ovarian cancer cells." (PMID 28938623, 2017). "MMP-2 and MMP-9 are especially prognostic for survival and metastatic potential in ovarian cancer." (PMID 28335466, 2017). "Additionally, LPA upregulates expression of matrix metalloproteinase-9 (MMP-9) and triggers MMP-9-catalyzed Ecad ectodomain shedding in a concentration- and time-dependent manner, disrupting junctional integrity in ovarian cancer cells and contributing to EMT." (PMID 28792442, 2017). "MMP-9 has been suggested as a potential therapeutic target for ovarian cancer therapy." (PMID 28538838, 2017). "MMP-9 expression is positively correlated with differentiation degree, FIGO staging and lymph node metastasis phase in ovarian cancer, but not with tissue types, suggesting that increased MMP-9 expression is associated with poor prognosis of ovarian cancer." (PMID 28538838, 2017). "MMP‐2 and MMP‐9 are upregulated in human ovarian carcinomas." (PMID 28401704, 2017). "Furthermore, the postoperative levels of MMP-9 in ovarian cancer are significantly reduced compared with preoperative levels." (PMID 28538838, 2017). "In the present study, we tested whether STAT3, phosphorylated at Tyr705, functions as a transcriptional activator, for positive regulation of MMP-9 in epithelial ovarian cancer." (PMID 28859117, 2017). "Here we found that IL-6 further promotes production of MMP-9 by ovarian cancer cells." (PMID 28859117, 2017). "Recently, it was found that inactivation of the NF-κB signaling by propofolabrogated gemcitabine-induced activation of NF-κB, resulting in the chemosensitizationof pancreatic cancer cells to gemcitabine.In aggressive ovarian cancers, NF-κB and NF-κB target gene MMP-9 are activated." (PMID 27982283, 2016). "Our findings showed that ovarian cancer cells could be induced to secrete MMP-9 in response to EGFR activation by physiological levels of HB-EGF." (PMID 27888810, 2016). "Here, Neu1 might be an intermediate candidate connecting the Snail-MMP9 signaling axis in tumor neovascularization and in promoting the growth and invasiveness of human triple negative breast and ovarian cancers." (PMID 27029067, 2016). "NF-κB has beenreported to regulate MMP-9 expression in ovarian cancer cells." (PMID 27982283, 2016). "Notably, we found that the activity of MMP-2 was much higher than the MMP-9 activity in ovarian cancer cells." (PMID 25686833, 2015). "Additionally, expression of VEGF by ovarian cancer cells is involved in transforming the ECM by stimulating MMP-9 expression at the tumor site." (PMID 26426054, 2015). "Snail and MMP9 acted as important mediators of PITX2-induced invasiveness of ovarian cancer cells." (PMID 26298390, 2015).
ovarian carcinoma (continued). "In this study, our IHC and immunoblotting results show that the decreased expression of MMP-9 in HeyA8-MDR-induced tumors could serve as an indicator of ovarian cancer treatment efficacy." (PMID 25788424, 2015). "Previously, we showed that RhoC promoted ovarian cancer invasion and metastasis through MMP9." (PMID 25649143, 2015). "Moreover, a direct link was shown by a strong reduction of invasion and adhesion of ovarian cancer cells after treatment with MMP-9 siRNA." (PMID 24466237, 2014). "CD147 as a partner of MCT1 is overexpressed under the hypoxic microenvironment and mediates cell proliferation and cycling, apoptosis, migration and invasion via activating VEGF and MMP-9 secretion, and vesicles shed from ovarian cancer cells to induce proangiogenic activities of HUVECs." (PMID 25268615, 2014). "Additionally, we have demonstrated that minocycline interferes with the metastatic potentials of ovarian cancer cells which was associated with suppression of MMP-2 and MMP-9." (PMID 23593315, 2013). "Moreover, basigin-2 protein expression was significantly correlated with survival and the expression level of MMP-2/MMP-9 and malignant metastasis of ovarian cancer." (PMID 23566400, 2013). "We propose that MMP-9/MMP-2i may be utilized in the treatment of recurrent/chemoresistant ovarian cancers that overexpress MMP-9 mRNA but its role in vivo remains to be evaluated." (PMID 23340649, 2013). "In addition, it seemed that EGF and HGF cooperate to promote invasiveness in ovarian cancer cell lines through increase secretion of MMP9 and the inhibition of MMP9 abolished EGF and HGF induced cellular invasion." (PMID 23320251, 2012). "Similarly, it has been shown that the invasion ability and MMP-9 levels in ovarian cancer cells are stimulated by HB-EGF expression." (PMID 22209887, 2012). "Based on the previous work and the co-cultured model of mouse embryos and human ovarian cancer cells, we take into account that in the co-culture environment whether the invasion behavior of ovarian cancer cells is in relation with MMP-9 expression." (PMID 22672566, 2012). "For example, extensive MMP-9 staining in ovarian cancer cells was associated with a longer survival, as opposed to a shorter survival with a higher stromal expression of MMP-9." (PMID 18506186, 2008). "Our results indicate that gelatinolytic activities of MMP-2 or MMP-9 are not required for collagen I invasion by ovarian cancer cells as treatment with the MMP-2/MMP-9 inhibitor SB-3CT caused only a small reduction in invasion." (PMID 17609667, 2007). "Trypsinogen, MMP-2, and MMP-9 are expressed in ovarian cancer." (PMID 11355948, 2001). "Consequently, we hypothesized that MICALL2 may promote EGFR-signaling activation and MMP9 expression in ovarian cancer cells." (PMID 38203692, 2023). "The results showed that MEnZn‐CuO NPs significantly downregulated the expression of MMP2 and MMP9, which are indicators of cell migration, and the phenotypic assays also suggested that the drug significantly inhibited the migration ability of both ovarian cancer cell lines." (PMID 37206208, 2023). "Collectively, these different signaling paradigms involved with EMT in ovarian cancer suggest that growth factor receptor glycosylation modification involving the receptor-signaling platform of a Neu1-MMP-9 crosstalk may be the invisible link connecting the Snail-MMP-9 signaling axis." (PMID 37626639, 2023). "Therefore, we next tested whether MICALL2 modulates the expression of MMP9 in ovarian cancer cells SKOV3." (PMID 38203692, 2023). "Moreover, in order to confirm the positive correlation between the expression of HK2 and p-Akt1, Fibronectin and MMP9 in human ovarian cancer tissues, serial sections of human ovarian cancer tissues (n = 25) were immunostained with antibodies specific for HK2, p-Akt1, fibronectin and MMP9." (PMID 35953860, 2022).